CSRP1 (cysteine and glycine rich protein 1)
Diseases named in the same sentence as CSRP1 in open-access papers (continued):
Sharing a sentence is not in itself a finding about the gene and the disease.
tumor (12 papers, 2008 to 2025). "Studies in vivo demonstrated that CSRP1 overexpression considerably reduces the LNCaP tumor growth compared to control group." (PMID 39994616, 2025). "These experiments demonstrated that lower expression levels of CSRP1 tend to enhance tumor cell proliferation, inhibit apoptosis, and promote migration." (PMID 39994616, 2025). "The results further supported the notion that low CSRP1 expression is conducive to accelerated tumor growth." (PMID 39994616, 2025). "The stromal scores generated by ESTIMATE, inferring the presence of stroma in tumor tissue, were significantly correlated with the CSRP1 expression in both the GSE39582 and TCGA COAD datasets (r > 0.45, p < 0.0001)." (PMID 38813484, 2023). "Single-cell RNA sequencing (scRNAseq) and immunohistochemistry (IHC) data indicated that CSRP1 was expressed by epithelial and stromal cells in the tumor microenvironment." (PMID 38813484, 2023). "Chi-square tests revealed that patients in high-CSRP1 protein expression group exhibited larger tumor size (P=0.003) and higher possibility of lymph nodes metastases (P=0.049)." (PMID 37113556, 2023). "According to statistically analyses, we found that patients with higher T stage showed elevated CSRP1-mRNA levels in their tumor specimens (P < 0.001)." (PMID 37113556, 2023). "The study also lacks validation regarding the detailed tumor-related effects of CSRP1 in COAD cells." (PMID 37113556, 2023). "In line with that, the data herein revealed the expression of CSRP1 mainly in epithelial cells and CAFs in the tumor microenvironment." (PMID 38813484, 2023). "The mRNA levels of CSRP1 are elevated in COAD specimens from patients with more advanced tumor stages and higher Carcinoembryonic Antigen (CEA) levels." (PMID 37113556, 2023). "Consistent with cellular data, the xenografts originated form CSRP1-knockdown cells showed significantly smaller tumor size and lighter tumor weight." (PMID 37113556, 2023). "Alternatively, the expression of CSRP1 in the tumor microenvironment of these tissues may be a critical factor underlying its relationships with disease progression." (PMID 38813484, 2023). "However, the tumor-suppressor-like expression and methylation changes of CSRP1 need further investigation since its relationship with poor prognosis was shown." (PMID 38813484, 2023). "Accordingly, a previously developed method, ESTIMATE, was utilized to assess whether the stromal fractions in the tumor microenvironment are correlated with the CSRP1 expression." (PMID 38813484, 2023). "Finally, we established a xenograft COAD model using nude mice to provide more data on the tumor-correlated effects of CSRP1." (PMID 37113556, 2023). "Therefore, CSRP1 seems to display completely different roles in different tumor types." (PMID 37113556, 2023). "Expression of CSRP1 is positively correlated with COAD progression, which can promote tumor growth and migration." (PMID 37113556, 2023). "Here, in the current study, we not only analyzed the clinical relevance between CSRP1 and COAD survival, but also validated its tumor-promoting effect through cellular and mice experiments." (PMID 37113556, 2023). "In order to further investigate the tumor-suppressing roles of MT1A, bayesian network models inferred that MT1A might positively regulate CSRP1." (PMID 38833013, 2024). "CSRP1 and MYL9 will decrease when tumor progressed from T2 to T4 (P = 0.032 and P = 0.047)." (PMID 35768705, 2022). "The expression of CSRP1, MYL9 and SNAI2 changed in different tumor stage." (PMID 35768705, 2022). "Identification of seven genes (MYLK, KLK2, KLK3, HAN11, LTF, CSRP1, TGM4) which have their connectivity altered between normal/tumoral conditions may provide novel insights into specific targets against tumor progression." (PMID 19055846, 2008).
tumor (continued). "Through pan-cancer analysis, we found that, unlike other tumor markers that are always highly or lowly expressed in different tumors, CSRP1 shows different expression patterns between different tumors, with CSRP1 highly expressed in 7 cancers and lowly expressed in 18 tumors." (PMID 38546813, 2024).
cancer (9 papers, 2010 to 2025). A tumor composed of atypical neoplastic, often pleomorphic cells that invade other tissues. "In recent years, research on CSRP1’s role in cancer has gained momentum, with its strongest associations being found in urogenital tumors." (PMID 39994616, 2025). "CSRP1, a smooth muscle marker that has a role in actin filament bundling, has been previously implicated in multiple cancer types." (PMID 38813484, 2023). "While research on CSRP1’s involvement in various cancers is advancing, its specific role in HSPC has yet to be fully explored and constitutes a significant gap in current knowledge, necessitating further investigation." (PMID 39994616, 2025). "It suggests that CSRP1 has a complex mechanism of regulation and can function as either an oncogene or oncogene suppressor in different cancer species or under different circumstances." (PMID 38546813, 2024). "The CSRP1 gene expression was evaluated in various cancer types and healthy tissues using publicly available datasets." (PMID 38813484, 2023). "Only a few reports have been made about CSRP1's connection to cancer thus far." (PMID 38546813, 2024). "Additionally, pan-cancer correlation analysis demonstrated that MT1A was most strongly correlated with CSRP1 in PRAD." (PMID 38833013, 2024). "The prognostic relationships of CSRP1 have been studied in several different cancer types." (PMID 38813484, 2023). "Therefore, CSRP1 may be related to cancer progression via various mechanisms related to proliferation, EMT, and cell migration." (PMID 38813484, 2023). "Therefore, CSRP1 may be related to different processes in cancers of different tissues of origin." (PMID 38813484, 2023). "Immunohistochemical analysis showed that 6 gene (NLRX1, AKT1, CSRP1, LEP, MUC4 and SEMA4B) of 10 genes were abnormal expressions between cancer and paracancer tissue." (PMID 36817485, 2023). "Therefore, development of CSRP1 inhibitors may provide new insights in cancer treatment." (PMID 37113556, 2023). "In addition, we observed the expression dysregulations of NLRX1, AKT1, CSRP1, LEP, MUC4 and SEMA4B in cancer tissues by immunohistochemistry." (PMID 36817485, 2023).
infection (2 papers, 2022 to 2025). The state of being infected such as from the introduction of a foreign agent such as serum, vaccine, antigenic substance or organism. "To investigate how MoSRP1 affects plant infection, we compared the infection process of srp1ko1 with that of P131 and cSRP1 on barley leaf epidermis." (PMID 36480554, 2022). "At 24 hpi, srp1ko1 remained in primary IH at 60% of infection sites, whereas P131 and cSRP1 developed the secondary IH at 70% of infection sites, at more than half of which, IH formed two branches." (PMID 36480554, 2022). "The GFP signals were concentrated in the nuclei of vegetative hyphae, conidia, appressoria, and infection hyphae of cSRP1." (PMID 36480554, 2022).
heart disease (1 paper, 2022). "The results of our EGRET analysis support a previously unreported mechanism of action for ERG that may be disrupted in heart disease—that ERG regulates the expression of CSRP1 and that this regulation can be disrupted by genetic variation." (PMID 35193937, 2022).
CSRP1 also shares sentences with these, for which no sentence is quoted: colorectal cancer (2 papers); astrocytomas (1); cardiovascular diseases (1); colorectal adenocarcinoma (1); liver cancer (1).